IGF2 (insulin like growth factor 2)
Diseases named in the same sentence as IGF2 in open-access papers (continued):
Sharing a sentence is not in itself a finding about the gene and the disease.
osteoarthritis (6 papers, 2019 to 2025). A noninflammatory degenerative joint disease occurring chiefly in older persons, characterized by degeneration of the articular cartilage, hypertrophy of bone at the margins and changes in the synovial membrane. "IGF2 also compromises ECM loss in inflamed chondrocytes and preserves cartilage integrity even in a model of experimental osteoarthritis." (PMID 35676242, 2022). "Lastly, prior studies demonstrated that IGF2 activates PI3K/AKT and MAPK pathways as downstream of IGF2 in osteoarthritis and cancer to promote proliferation, survival, and disease progression 61-63." (PMID 40384861, 2025).
pheochromocytoma (6 papers, 2015 to 2026). "Overexpression of IGF2 transcript is common in phaeochromocytomas, and mechanisms found so far are tumour- specific genomic changes in copy number, uni-parental disomy, and methylation." (PMID 34170845, 2021). "Thus, there are several possible mechanisms by which genomic changes activating transcription from the IGF2 gene also could increase the expression of the INS gene in phaeochromocytoma." (PMID 34170845, 2021). "Therefore, we tested whether insulin transcript (INS), insulin, and a hybrid read-through transcript between exons from insulin and insulin-like growth factor 2 (INS-IGF2) were expressed in phaeochromocytomas." (PMID 34170845, 2021).
viral infection (6 papers, 2004 to 2024). "In the further virus infection assays, GaHV-2-encoded miR-M2-5p also showed similar down or up regulations of the expressions of gga-miR-223 and IGF2." (PMID 33224130, 2020). "Our study sheds new light on the intrathymic regulation of Igf2 transcription during CV-B4 infections and supports the hypothesis that a viral infection can disrupt central self-tolerance to insulin by decreasing Igf2 transcription in the thymic epithelium." (PMID 33672010, 2021). "However, the present study is the first to show a direct connection between Igf2 gene expression and resistance to lytic virus infection." (PMID 15333144, 2004). "Overall, these data confirm that the secreted IGF2RD11mt serves as a decoy receptor against both human and murine IGF2 without altering the efficiency of viral infection and replication." (PMID 38853689, 2024).
colitis (5 papers, 2022 to 2026). Inflammation of the colon. "In DSS-induced colitis models, IGF2 levels were reduced, but recombinant IGF2 restored IGF2R expression, blocked cGAS-STING signaling, preserved tight junction proteins (ZO-1, occludin), and promoted epithelial regeneration." (PMID 40507791, 2025). "A low dose of IGF2 (≤ 50 ng per mouse) alleviated colitis and inhibited inflammation, while high doses of IGF2 (1000 ng per mouse) failed to ameliorate colitis and instead exacerbated its progression and promoted inflammation." (PMID 38017373, 2023). "As an example, MuSCs can act on maturing macrophages and confer them with oxidative phosphorylation-dependent anti-inflammatory properties via insulin-like growth factor-2 (IGF-2), thus ameliorating dextran sulfate sodium (DSS)-induced colitis." (PMID 37507432, 2023). "It has been found that IGF2 in low dose acts through IGF2R and alleviates colitis via promoting anti-inflammatory macrophages, suggesting that IGF2 family strongly controls generation of anti-inflammatory macrophages and may provide novel strategies for the treatment of inflammatory diseases." (PMID 35378790, 2022).
diabetic nephropathy (5 papers, 2012 to 2023). "IGF-binding protein 2 (IGFBP2) and IGF2 are expressed in the kidney, but their associations with diabetic nephropathy are unclear." (PMID 23781310, 2012). "INS rs3842753 with a derived allele frequency of more than 75% in non-African populations has been identified as a marker for atypical T2D in the Uruguayan population, while IGF2 rs10770125 has been associated with diabetic nephropathy in people with European American ancestry." (PMID 32171244, 2020). "Interestingly, the upregulation of IGF2 in diabetic nephropathy (DKD) has also been proposed following analysis of renal biopsies from normal (n = 9) and early T2DM patients with (n = 9) or without (n = 11) histopathological characteristics of DKD." (PMID 36982475, 2023). "In a separate study of European American descents in the GoKinD project, IGF2 rs10770125 has been associated with diabetic nephropathy in male patients with T1D, but not in female patients." (PMID 32171244, 2020). "Research with respect to the interactions of IGF2 in diabetic kidney disease has been limited." (PMID 23781310, 2012).
liver cirrhosis (5 papers, 2010 to 2022). "IGF2 has several roles in the development of liver cirrhosis and HCC through the promotion of hepatocyte proliferation." (PMID 34714420, 2021). "ROC analysis showed that IGF2 had the highest area under the curve (AUC) for discriminating HCC from liver cirrhosis (0.86), followed by IL6 (0.82), AFP (0.72), and platelet count (0.6)." (PMID 34714420, 2021). "The studies on IGF2 in liver cirrhosis indicate that IGF2 plays a role in cell proliferation of regenerating nodules, as well as in the development of HCC." (PMID 29702590, 2018). "Some other studies also suggested that, in liver cirrhosis and in some benign liver tumors, premalignant proliferative states might be identified by the presence of IGF2 fetal transcripts." (PMID 29702590, 2018). "Hypomethylation at the IGF2 locus may be predictive for HCC in cases of liver cirrhosis and hepatitis C infection." (PMID 29702590, 2018). "Different values of lowered serum concentration of both IGFs were proposed as a negative prognostic factor in patients with liver cirrhosis (IGF1: 13, 30 ng/mL; IGF2: below 200 ng/mL)." (PMID 29702590, 2018).
liver fibrosis (5 papers, 2014 to 2025). "Similar to our results, it has been reported that lower levels of IGF2 in plasma are associated with more severe liver fibrosis in patients with non-alcoholic fatty liver disease." (PMID 38017373, 2023). "IGF2 is involved in inflammation and fibrosis, and the IGF2 plasma levels were closely associated with the stages of liver fibrosis." (PMID 33746571, 2021). "For example, plasma IGF-2 and EGFR can be used as diagnostic markers for liver fibrosis in obese patients." (PMID 36358907, 2022). "IGF-2 enrichment can be observed in proliferating hepatocytes from patients with liver fibrosis." (PMID 36358907, 2022). "NK cells with a high killing effect can kill HSCs and thus inhibit liver fibrosis, and some investigators have suggested that IGF-2 may promote the killing effect of NK cells through the START3 signaling factor." (PMID 36358907, 2022). "Interestingly, miR-483 is embedded in the second intron of the Igf2 gene, which is overexpressed in liver fibrosis and HCC." (PMID 24801603, 2014). "In both a carbon tetrachloride (CCl4)-induced mouse model of liver fibrosis and a 2-fluorenylacetamide (2-FAA)-induced rat model of liver fibrosis, hepatocytes overexpressed IGF-2." (PMID 36358907, 2022). "Igf2 overexpression was observed during the progression from liver fibrosis to HCC, and IGF2 promoted proliferation and carcinogenesis." (PMID 24801603, 2014).
male infertility (5 papers, 2020 to 2024). The inability of the male to effect fertilization of an ovum after a specified period of unprotected intercourse. "If future studies confirm the role of sperm-carried IGF2 in human fertility, this may become a novel diagnostic and/or therapeutic target in the field of apparently idiopathic male infertility." (PMID 32138324, 2020). "Methylation anomalies of the H19, IGF2, GNAS, GNASAS, and MEST imprinted genes have not previously been associated with male infertility based on transcriptome data." (PMID 39017772, 2024).
omphalocele (5 papers, 2010 to 2025). Omphalocele is an embryopathy classified in the group of abdominal celosomias and is characterized by a large hernia of the abdominal wall, centered on the umbilical cord, in which the protruding viscera are protected by a sac. "The IC1 hypermethylation subtype is characterized by a higher frequency of body overgrowth and visceromegaly, likely due to IGF2 overexpression, and a relatively lower frequency of ear creases, ear pits, facial nevus flammeus, and omphalocele." (PMID 40518523, 2025). "A well-defined (epi)genotype–phenotype correlation exists for omphalocele in BWS: it is caused by KCNQ1OT1:TSS-DMR loss of methylation in 86% of the cases, by CDKN1C mutation in 7%, and by UPD or H19/IGF2:IG-DMR gain of methylation in <10% of patients." (PMID 29047350, 2017). "We can surmise that alterations of methylation levels at H19/IGF2:IG-DMR and KCNQ1OT1:TSS-DMR are not primarily associated to omphalocele, in our cohort; conversely, sequence variants at KCNQ1OT1:TSS-DMR and CDKN1C could represent susceptibility factors for the onset of isolated omphalocele." (PMID 29047350, 2017).
renal cell carcinoma (5 papers, 2008 to 2024). "NEAT1, THOR, and HOTTIP via targeting IGF2 affect carcinogenic processes in colorectal cancer, tongue squamous cell carcinoma, and renal cell carcinoma." (PMID 33768092, 2021). "A study reported that overexpression of circ-FNDC3B may weaken the effects of curcumin on inhibiting proliferation and promoting apoptosis of RCC cell through regulating the miR-138-5p/IGF2 axis, which provides a new perspective for the treatment of renal cell carcinoma." (PMID 35223991, 2022).
Sepsis (5 papers, 2014 to 2025). Sepsis is defined as life-threatening organ dysfunction caused by a dysregulated host response to infection. "For example, Circexoc5 enhances ferroptosis and exacerbates sepsis-induced ALI via the IGF2 BP2/ATF3 signaling pathway." (PMID 40811488, 2025). "False positives may be seen with sepsis and cachexia as both IGF-2 and IGF-1 are subnormal in these cases." (PMID 38432069, 2024). "A falsely elevated ratio may be seen in patients with sepsis or cachexia due to subnormal IGF-2 and IGF-1 levels in these cases." (PMID 38432069, 2024). "Although IGFBP6-mediated regulation of CCL2 is independent of IGF2, the potential involvement of IGF2-dependent pathways in IGFBP6’s modulation of sepsis progression remains an open question requiring systematic investigation." (PMID 40892465, 2025).
adrenal tumors (4 papers, 2012 to 2025). "Our data provide conclusive evidence that loss of the maternal allele correlates with IGF2 overexpression in adrenal tumors and that hypermethylation of the H19 ICR is a consequence thereof." (PMID 26400872, 2015). "28/38 adrenal tumors with LOH of the IGF2/H19 locus had lost the maternal allele and gained an extra copy of the paternal allele." (PMID 26400872, 2015). "In conclusion, our data suggest that IGF2 overexpression in adrenal tumors correlates mainly with allelic loss leading to an imbalance of the ratio between paternal and maternal alleles and that the aberrant DNA methylation levels observed for the H19 ICR are a consequence thereof." (PMID 26400872, 2015). "The exact mechanisms underlying IGF2 overexpression in adrenal tumors are poorly understood." (PMID 26400872, 2015). "The mechanisms accounting for the late involvement of Igf2 in adrenal tumour progression are unclear." (PMID 22952916, 2012). "This suggests that Igf2 overexpression is dispensable in the early stages of adrenal tumour development, which is consistent with the low expression of IGF2 in human ACA." (PMID 22952916, 2012). "In the current study, we provide the first integrated analysis of gene expression, DNA methylation and genetic variation of the IGF2/H19 locus in adrenal tumor subtypes using high-resolution molecular technologies to unravel the driving force behind IGF2 overexpression in these tumors." (PMID 26400872, 2015). "Gene expression changes of IGF2 and H19 were analyzed in 60 fresh frozen adrenal tumors." (PMID 26400872, 2015). "It is therefore tempting to speculate that one of the effects of Igf2 overexpression in adrenal tumour progression is dependent on an increased translation capacity, resulting from phosphorylation and activation of the S6 protein." (PMID 22952916, 2012). "In the present study we therefore integrated IGF2 and H19 expression levels with the DNA methylation levels of three regulatory DMRs located throughout the IGF2/H19 locus and compared this to the copy number status and ploidy of chr11p15.5 in a cohort of 62 adrenal tumor samples." (PMID 26400872, 2015). "Our analysis of these models shows that Igf2 overexpression does not induce adrenal tumour development although it triggers aberrant recruitment of adrenal progenitors cells in a hedgehog independent manner." (PMID 22952916, 2012). "Here, we show that overexpression of Igf2 from 7 to 87 fold over basal levels does not result in adrenal tumour formation in transgenic mice over 14 months, despite a mild increase in cortical cell proliferation." (PMID 22952916, 2012). "This suggested that Igf2 overexpression might not initiate adrenal tumour development but that it could be involved in malignant progression." (PMID 22952916, 2012). "Although IGF2 on its own is not sufficient for transformation, it has an active role in promoting ACC tumor growth and the IGF family plays an important role for the development of adrenal tumors, and has been proposed as therapeutic target." (PMID 26400872, 2015).
amyotrophic lateral sclerosis (4 papers, 2021 to 2025). Amyotrophic lateral sclerosis (ALS) is a neurodegenerative disease characterized by progressive muscular paralysis reflecting degeneration of motor neurons in the primary motor cortex, corticospinal tracts, brainstem and spinal cord. "IGF2, is a secreted factor which has been recently recognized with interesting neuroprotective activities in several models of neurodegenerative diseases, including AD, Amyotrophic Lateral Sclerosis and HD." (PMID 38042807, 2023).
Angelman syndrome (4 papers, 2021 to 2024). A neurogenetic disorder characterized by severe intellectual deficit and distinct facial dysmorphic features. "Recent studies have highlighted the beneficial effects of IGF-2 in ameliorating cognitive deficits in aged-rats, in the BTBR mouse model of ASDs and in the Ube3A maternal-deficient (m-/p +) mouse model of Angelman syndrome." (PMID 38298376, 2023). "The effects of IGF-2 in rats and mice on either memory enhancement or the recovery of behavioral impairments in mouse models of neurodevelopmental disorders (ASD and Angelman syndrome) is very rapid and, in fact, are detected by 20 min after injection." (PMID 38298376, 2023). "Interestingly, experiments performed on a murine model of Angelman syndrome (AS, MIM#105830), a disease included in the differential diagnosis of PTHS, showed a behavioral rescue following acute systemic IGF-2 treatment." (PMID 39594970, 2024).
autism spectrum disorder (4 papers, 2021 to 2025). A spectrum of developmental disorders that includes autism, and Asperger syndrome. "In this study, through the analysis of CHD8A and CHD8B allelic deletion samples, we identified seven hub genes associated with Autism Spectrum Disorder (ASD): IGF2, FN1, CXCR4, COL11A1, ITGA6, LOX, and FBN2." (PMID 40526590, 2025). "CXCR4 and IGF2 play critical roles in neuronal migration and differentiation, and their dysregulation has been linked to abnormal neurodevelopment associated with Autism Spectrum Disorder (ASD)." (PMID 40526590, 2025). "In BTBR T+ Itpr3tf/J mice that display a behavioral phenotype similar to that of autism-spectrum disorders, IGF-2 injection reversed the cellular abnormalities associated with protein overproduction." (PMID 33673334, 2021). "IGF2 has also been associated with autism spectrum disorders and similar phenotypes." (PMID 33834688, 2021). "In a mouse model of autism spectrum disorders (ASD), BTBR T+ Itpr3tf/J strain, IGF-2 injection reversed the cellular abnormalities associated with protein overproduction: activation of the AMPK-mTOR-S6K pathway, increased translation in synapses and decreased autophagy level." (PMID 33673334, 2021).
benign prostatic hyperplasia (4 papers, 2011 to 2024). A non-cancerous nodular enlargement of the prostate gland. "The hypomethylation of IGF2-DMR0 is associated to lower IGF2 expression in PCa tissues compared to benign prostate hyperplasia." (PMID 39135777, 2024).
Bladder tumor (4 papers, 2017 to 2025). "Loss of imprinting (LOI) in IGF2 and an aberrant IGF2 expression have been reported in human tumors of bladder, esophagus, colon, breast and prostate." (PMID 29017567, 2017). "For instance, the UBC® Rapid test and UBC ELISA kit, the XPERT BC Monitor, BC UroMark, TaqMan® Arrays, Soluble FAS (sFAS), Bladder tumor fibronectin (BTF), and IGF2 and MAGE-A3 are among the newest biomarkers under investigation." (PMID 39678505, 2024). "There are studies that have reported the negative correlation between insulin-like growth factor 2 messenger RNA-binding protein 3 (IGF2BP3) and the prognosis of various tumors, such as bladder tumor prognosis." (PMID 37505298, 2024).
chronic myeloid leukemia (4 papers, 2013 to 2023). "In chronic myeloid leukemia cells IGF2BP3 depletion determined a reduction of IGF2 production and increased susceptibility to ionizing radiation as measured by apoptosis, effect that was partially reversed by treatment with recombinant IGF2." (PMID 33673232, 2021).
gastric adenocarcinoma (4 papers, 2021 to 2024). "In stomach/gastric adenocarcinoma, IGF2 and CCNE1 were identified as enhancer hijacking target genes in a cohort of 208 samples." (PMID 39051548, 2024). "Expression of insulin receptor isoform A, for which IGF-1 and IGF-2 have higher affinities than they have for isoform B, by gastric adenocarcinoma cells makes this supposition plausible." (PMID 34554347, 2022). "High tumour IGF1 and IGF2 expression, IGF2 is the 25th most over-expressed gene in gastric adenocarcinoma, implies local IGF-1 and IGF-2 synthesis." (PMID 34554347, 2022). "Relatively higher expression of insulin receptor isoform B, for which insulin has considerably higher affinity than IGF-1 or IGF-2 has, was apparent in metastatic gastric adenocarcinoma cells." (PMID 34554347, 2022). "INS, IGF1 and IGF2 mRNAs were measured in a separate cohort of 1065 gastric adenocarcinomas by microarray hybridisation." (PMID 34554347, 2022). "Twenty-five gastric adenocarcinomas had relative IGF-2 mRNA abundances ≥ 20,000 (14.29 log2) of which only three had concurrent gene amplification." (PMID 34554347, 2022). "Tumour synthesis coupled with demonstration that IGF-1 and IGF-2 stimulate gastric adenocarcinoma cell growth and survival, suggests potential autocrine activity." (PMID 34554347, 2022). "The relative EC50 values for insulin-stimulated protein phosphorylation in gastric adenocarcinoma cells, 1.2–5 ngml−1 (0.2–2.6 nM) were similar to those of IGF-1 and IGF-2." (PMID 34554347, 2022). "Proliferative effects of insulin on gastric adenocarcinoma cells were compared to those of IGF-1 and IGF-2." (PMID 34554347, 2022). "Incubation of gastric adenocarcinoma cells with different insulin, IGF-1 or IGF-2 concentrations prior to induction of apoptosis demonstrated concentration-dependent protection." (PMID 34554347, 2022). "Dependence of gastric adenocarcinoma cell survival upon insulin receptor but not type I IGF receptor indicates that IGF-1 and IGF-2 promote cell survival through the insulin receptor." (PMID 34554347, 2022).
growth deficiency (4 papers, 2015 to 2021). "For example, animal studies have shown that biallelic expression of Igf2 results in overgrowth, whereas deletion of the Igf2 gene results in growth deficiency." (PMID 34440327, 2021). "In particular, IGF2 is maternally imprinted, and disrupting mutations inherited from the male germline cause growth deficiency in mice." (PMID 30581455, 2018).